SEC24A (SEC24 homolog A, COPII component)
Description:
Component of the coat protein complex II (COPII) which promotes the formation of transport vesicles from the endoplasmic reticulum (ER). The coat has two main functions, the physical deformation of the endoplasmic reticulum membrane into vesicles and the selection of cargo molecules for their transport to the Golgi complex. Plays a central role in cargo selection within the COPII complex and together with SEC24B may have a different specificity compared to SEC24C and SEC24D. May package preferentially cargos with cytoplasmic DxE or LxxLE motifs and may also recognize conformational epitopes.
Tractability: Small molecule: a structure with a bound ligand is known. Antibody: UniProt places it where antibodies can reach, with high confidence. PROTAC: ubiquitination databases record sites on it; its protein half-life has been measured.
Gene: Protein-coding gene on chromosome 5 (134,648,588 to 134,727,909, forward strand). Ensembl gene ENSG00000113615.
Subcellular location: Cytoplasmic vesicle, COPII-coated vesicle membrane; Endoplasmic reticulum membrane; Cytoplasm, cytosol
Subcellular location (Human Protein Atlas): Nucleoli fibrillar center; Vesicles
Pathways (Reactome):
Immune System: Antigen Presentation: Folding, assembly and peptide loading of class I MHC; MHC class II antigen presentation
Vesicle-mediated transport: COPII-mediated vesicle transport; Cargo concentration in the ER
Disease: SARS-CoV-2 activates/modulates innate and adaptive immune responses
Metabolism: Regulation of cholesterol biosynthesis by SREBP (SREBF)
Gene Ontology:
Molecular function: protein binding; zinc ion binding; SNARE binding
Biological process: COPII-coated vesicle cargo loading; endoplasmic reticulum to Golgi vesicle-mediated transport; positive regulation of ER to Golgi vesicle-mediated transport; intracellular protein transport
Cellular component: COPII vesicle coat; cytosol; endoplasmic reticulum; endoplasmic reticulum membrane; ER to Golgi transport vesicle membrane
Genetic constraint (gnomAD): Loss-of-function variants: 46 observed, 66.62 expected, observed/expected ratio (o/e) 0.69, 90% interval 0.54 to 0.88. The upper end of that interval is the gene's LOEUF score, 0.88, which puts it in group 3 of 6, group 1 being the genes least tolerant of losing a copy. Missense variants: 799 observed, 840.41 expected, observed/expected ratio (o/e) 0.95, 90% interval 0.9 to 1.01. Synonymous variants: 281 observed, 311.25 expected, observed/expected ratio (o/e) 0.9, 90% interval 0.82 to 1.
Homologues: Orthologues: chimpanzee SEC24A (99% identical), macaque SEC24A (98% identical), rabbit SEC24A (93% identical), dog SEC24A (93% identical), pig SEC24A (90% identical), mouse Sec24a (88% identical), rat Sec24a (88% identical), guinea pig SEC24A (84% identical), tropical clawed frog sec24a (72% identical), zebrafish sec24a (60% identical), Drosophila melanogaster Sec24AB (43% identical), Caenorhabditis elegans sec-24.2 (36% identical). Paralogues in human: SEC24B (60% identical), SEC24D (25% identical).
Diseases named in the same sentence as SEC24A in open-access papers:
SEC24A is named in the same sentence as 10 diseases in open-access papers, as found by Europe PMC text mining. Sharing a sentence is not in itself a finding about the gene and the disease. The quoted sentences say what the papers report.
Hypocholesterolemia (1 paper, 2013). An decreased concentration of cholesterol in the blood. "Although this reduction in plasma cholesterol was less than observed in Sec24agt/gt mice, considering the incomplete deletion of hepatic Sec24a by Adv-Cre, these data suggest that loss of hepatic Sec24a expression is sufficient to explain the hypocholesterolemia observed in SEC24A-deficient mice." (PMID 23580231, 2013).
Insulin resistance (1 paper, 2012). Increased resistance towards insulin, that is, diminished effectiveness of insulin in reducing blood glucose levels. "In this study, increased abundance of Sec24a, glutathione S-transferase, and derlin-2 may suggest that ER stress contribute to the insulin resistance in the high fat fed mice." (PMID 33907358, 2012).
osteoporosis (1 paper, 2024). A condition of reduced bone mass, with decreased cortical thickness and a decrease in the number and size of the trabeculae of cancellous bone (but normal chemical composition), resulting in increased fracture incidence. "Subsequently, we detected the expression of Sec24a, Sec31a, LC3‐II, and Beclin1 using immunohistochemistry, and identified that these proteins decreased during osteoporosis in rats." (PMID 39361436, 2024).
infection (2 papers, 2017 to 2025). The state of being infected such as from the introduction of a foreign agent such as serum, vaccine, antigenic substance or organism. "We found a minimal effect on infection when we singly depleted the four isoforms: Sec24a (p-value 0.0192), 24b (p-value 0.0020), 24c (p-value not significant), or 24d (p-value 0.0018), consistent with described functional redundancy." (PMID 40431628, 2025).
SEC24A also shares sentences with these, for which no sentence is quoted: cancer (2 papers); tumor (2); dyslipidemia (1); hepatoma (1); lymphoma (1); periodontitis (1).